BLM (BLM RecQ like helicase)
Diseases named in the same sentence as BLM in open-access papers (continued):
Sharing a sentence is not in itself a finding about the gene and the disease.
glioma (3 papers, 2023 to 2025). A benign or malignant brain and spinal cord tumor that arises from glial cells (astrocytes, oligodendrocytes, ependymal cells). "BLM-depleted glioma cells exhibit senescence-associated or polypoid phenotype when exposed to temozolomide (TMZ) and olaparib (OLA), a PARP inhibitor." (PMID 41023983, 2025). "We determined if RECQL4 variants (which altered interactions with BLM and DNA repair) affect glioma cell responses to TMZ, a main chemotherapeutic in glioma therapy." (PMID 41419455, 2025). "WT and mutated RECQL4 were overexpressed in RECQL4 KO glioma cells to study interactions with BLM helicases, cell viability and specific responses to UVC- and chemotherapy-induced DNA damage/repair." (PMID 41419455, 2025). "BLM deficiency in glioma cells changes their responses to chemotherapy and shifts their responses to apoptosis, polyploidy or cell senescence." (PMID 37169803, 2023). "BLM deficiency in glioma LN18 and LN229 cells reduced their proliferation and LN18 BLM KO cells were significantly arrested in the G2/M phase." (PMID 37169803, 2023). "We found that BLM deficient glioma cells become resistant to the combined TMZ and PARP1 inhibitor treatment and respond with polyploidy or cellular senescence." (PMID 37169803, 2023). "BLM deficiency affects responses of glioma cells to chemotherapeutics targeting PARP1 dependent pathways." (PMID 37169803, 2023). "BLM deficiency changes the way glioma cells respond to drugs and sensitises KO cells to therapeutics." (PMID 37169803, 2023). "As BLM participates in the correct chromosome segregation and resolving anaphase bridges, its deficiency in T + O-treated glioma cells may lead to the cytokinesis failure." (PMID 37169803, 2023). "The BLM mutations resulting in alterations in the nuclear targeting signal (NLS) domain or dysregulation of mechanisms responsible for nuclear targeting might be another reason for mis-localisation of BLM in glioma cells." (PMID 37169803, 2023). "RECQL4 depletion modestly affected basal glioma cell viability and proliferation, similarly to knock out of the BLM protein." (PMID 41023983, 2025). "The interaction of RQ4m1 with the BLM helicase was impaired in LN18 glioma cells, while in LN229 cells this binding was decreased, although insignificantly." (PMID 41419455, 2025). "The newly identified RECQL4 mutations affect RECQL4 helicases and their interactions with BLM contributing to glioma progression." (PMID 41419455, 2025). "We found RECQL4 and BLM expression upregulated at mRNA and protein levels in GBMs and glioma cell lines." (PMID 41419455, 2025). "Transcriptomic analysis revealed distinct gene expression patterns between RQ4 and BLM KO glioma cells, particularly in cell cycle–related transcripts, highlighting functional differences between these two RecQ helicases." (PMID 41023983, 2025). "The graph shows that depletion of either RECQL4 or BLM has different consequences in different glioma cells, with disturbances of cell cycle related genes noteworthy in RQ4 KO LN229 cells." (PMID 41023983, 2025). "Depletion of RECQL4 or BLM in human glioma cells by CRISPR/Cas9 editing resulted in profound changes in the transcriptome, reduction of glioma sphere formation and augmented vulnerability to chemotherapeutics." (PMID 41419455, 2025). "RECQL4 or BLM depletion in glioma cells moderately affected cells viability, however LN229 cells displayed minimally increased sensitivity to helicases knock out." (PMID 41023983, 2025). "We found markedly upregulated RECQL4 and BLM at mRNA and protein levels in GBMs, while their protein levels were low in lower grade gliomas." (PMID 41023983, 2025).
glioma (continued). "These transcriptomics analyses show that ECM organization is one of the prominent and shared pathways between RQ4 and BLM KO glioma cells, while RECQL4 deficiency has a stronger impact on the cell cycle than BLM deficiency." (PMID 41023983, 2025). "We show slight sensitisation the BLM KO glioma cells to TMZ alone and distinct responses of BLM-deficient glioma cells to TMZ, OLA and T + O." (PMID 37169803, 2023). "BLM KO and WT glioma cells were subjected to RNA sequencing and differentially expressed genes (DEG) were identified." (PMID 37169803, 2023). "Despite the importance of BLM in DNA repair and other processes, its involvement in glioma progression and responses of GBM cells to cytotoxic drugs have not been studied." (PMID 37169803, 2023). "While BLM protein levels differed between the glioma cells, the highest level of BLM protein was detected in LN18 and LN229 cells." (PMID 37169803, 2023). "We performed comprehensive analyses of BLM expression and functions in GBMs and demonstrated high levels of the BLM mRNA and protein in malignant tumours and glioma cell lines, along with abnormal cytoplasmic accumulation of BLM in GBMs." (PMID 37169803, 2023). "Inspired by findings that BLM is overexpressed in many tumours, we analysed the BLM expression across the glioma patients using the transcriptomic dataset from the Cancer Genome Atlas (TCGA)." (PMID 37169803, 2023). "BLM protein levels were elevated in all 7 tested glioma cell lines when compared to normal human astrocytes." (PMID 37169803, 2023). "BLM deficiency in human LN18 and LN229 glioma cells affected cell growth, viability and responses to chemotherapeutics." (PMID 37169803, 2023). "In control brains and low grade gliomas most of the BLM staining was nuclear whereas both nuclear and cytoplasmic localisation of BLM was detected in malignant gliomas." (PMID 37169803, 2023). "As BLM expression is upregulated in many tumours including GBMs, we sought to define the role of BLM helicase in human glioma cells and their vulnerability to clinically used chemotherapeutics." (PMID 37169803, 2023). "The analysis of transcriptomic changes in WT and BLM KO cells untreated or treated with the combination of T + O revealed a set of common genes upregulated and downregulated in drug-treated BLM KO glioma cells." (PMID 37169803, 2023). "We analysed expression and localisation of BLM in human gliomas and several glioma cell lines using TCGA datasets, immunostaining and Western blotting." (PMID 37169803, 2023). "KEGG analysis of DEGs showed many dysregulated functional pathways, when compared to untreated BLM KO glioma cells." (PMID 37169803, 2023). "We investigated if BLM deficiency would affect sensitivity of human glioma cells to chemotherapeutics, thus we treated LN18 and LN229 BLM WT and KO cells with TMZ, OLA or with TMZ and OLA combination." (PMID 37169803, 2023). "BLM deficiency in LN18 and LN229 glioma cells resulted in profound transcriptomic alterations, reduced cell proliferation, and altered cell responses to chemotherapeutics." (PMID 37169803, 2023). "However, we found that RECQL4P532S binds strongly BLM in LN18 cells, and RECQL4R766Q restricts BLM in the cytoplasm of LN229 glioma cells, particularly when DNA damage was inflicted by UV-C irradiation." (PMID 41419455, 2025). "We have previously shown that BLM co-localizes with γH2AX in UV-C irradiated human glioma cells." (PMID 41419455, 2025). "Interestingly, certain BLM KO glioma cells are insensitive to the combination of TMZ and PARPi but not with other chemotherapeutics, it shows a need for better diagnostics and patient stratification." (PMID 37169803, 2023).
glioma (continued). "With genetic alterations in the BLM gene reported in gliomas, manipulation of the BLM level could be additional strategy to improve the therapeutic option for patients with deadly brain tumours." (PMID 37169803, 2023). "We determined the BLM mRNA and protein levels in seven human glioma cell lines: established T98, LN229, U251, LN18, U87 cell lines and patient-derived primary WG4, WG9 cell cultures; normal human astrocytes (NHA) and normal brain (NB) served as a non-malignant control." (PMID 37169803, 2023). "Moreover, RECQL4 and BLM KO reduced cell proliferation in glioma cells in a range of 10–20%." (PMID 41023983, 2025). "We focused on significant transcriptomics changes (differentially expressed genes, DEGs) in LN18 and LN229 KO glioma cells in comparison to respective WT controls, and compared DEGs in RQ4 KO and BLM KO cells." (PMID 41023983, 2025). "Overexpression of RECQL4P532S or RECQL4R766Q variants affected DNA repair and responses to chemotherapeutics in glioma cells, and RECQL4R766Q disturbed interactions with the BLM helicase." (PMID 41419455, 2025). "We analysed the levels of RECQL4 and BLM proteins in LN18 and LN229 glioma cells depleted of respective proteins." (PMID 41023983, 2025). "As WP744 induces the apoptotic cells death in glioma cells, the presented results suggest specific functions for RECQL4 and BLM helicases in chemotherapeutics- induced apoptosis." (PMID 41023983, 2025). "Representative images show cell rounding and detachment in WT glioma cells treated with WP744, while RQ4 KO and BLM cells remained unchanged morphologically." (PMID 41023983, 2025). "We found elevated expression of BLM in gliomas of WHO grades 1–4, with the highest median expression of BLM in WHO grade 4 GBMs." (PMID 37169803, 2023). "Interestingly, both RQ4 KO and BLM KO cells were more resistant to WP744, a doxorubicin derivative, when compared to WT LN229 glioma cells." (PMID 41023983, 2025). "In LN229 cells, where most cells die by apoptosis after TMZ, overexpression of RECQL4 variants produced weaker effects on the BLM signal and γH2AX foci in TMZ-treated glioma cells, and the changes were not significant." (PMID 41419455, 2025). "WP744 effectively impaired WT human glioma cell viability, when compared to RQ4 KO or BLM KO cells." (PMID 41023983, 2025). "Overexpression of RECQL4-GFP variants in LN18 cells did not change the appearance of γH2AX and BLM foci in UVC-treated glioma cells." (PMID 41419455, 2025). "We compared transcriptomes of RECQL4- and BLM-depleted LN18 and LN229 glioma cells." (PMID 41023983, 2025). "Quantification of the staining results revealed the negative correlation between nuclear BLM positivity and glioma grades (pie charts)." (PMID 37169803, 2023). "Interestingly, we reported for a first time that BLM is localised mostly in a cytoplasm of malignant gliomas (WHO grades 3 and 4) while in normal brain and low grade gliomas BLM was located primarily in the nuclei." (PMID 37169803, 2023). "We do not have a plausible explanation why knockdown of BLM in glioma cells makes PARP inhibition ineffective." (PMID 37169803, 2023). "Therefore, we sought to determine how a lack of RECQL4 or BLM in glioma cells would affect cell responses to therapy." (PMID 41023983, 2025). "In contrast to BLM KO cells, such treatment did not induce senescence (based on β-gal-positive cells) or polyploidisation in RQ4 KO glioma cells." (PMID 41023983, 2025).
invasive breast carcinoma (3 papers, 2021 to 2023). A carcinoma that infiltrates the breast parenchyma. "Rad51, NEIL3 and BLM, which were linked to invasive breast cancer and BRIP1 that was associated with IDC and LC, are the only genes to our knowledge that were previously linked to invasive breast carcinoma." (PMID 33662042, 2021). "BLM facilitates the growth of invasive breast cancer by enhancing the duplication of DNA and the multiplication of cells." (PMID 37626815, 2023).
Lynch syndrome (3 papers, 2018 to 2021). An autosomal dominant hereditary neoplastic syndrome characterized by the development of colorectal carcinoma and a high risk of developing endometrial carcinoma, gastric carcinoma, ovarian carcinoma, renal pelvis carcinoma, and small intestinal carcinoma. "Of these, five mutations (9.26%, 5/54) were in homologous recombination repair (HRR) pathway genes, including PALB2 (1.85%, 1/54), BLM (1.85%, 1/54), NBN (1.85%, 1/54), RAD51C (1.85%, 1/54), and RAD51D (1.85%, 1/54), and one mutation was in MSH3 (1.85%, 1/54) related to Lynch syndrome." (PMID 33194720, 2020).
neuroblastoma (3 papers, 2015 to 2025). Neuroblastoma (NB) is the most common solid, extracranial childhood tumor. "Cocktails of small molecule inhibitors of CKS1B, AHCY, BLM, and PKMYT1 profoundly affected the growth of all neuroblastoma cell lines but selectively caused death of MYCN-amplified cells." (PMID 25477524, 2015). "To verify the role of BLM in neuroblastoma, we examined the expression of phosphorylated histone γ-H2AX, used as a marker for DNA double-stranded breaks, after infection of neuroblastoma cells with a BLM shRNA." (PMID 25477524, 2015). "The significance of BLM, AHCY, PKMYT1, and CKS1B in the pathogenesis of neuroblastoma is indicated by their elevated expression in MYCN-amplified tumor samples and in MYCN-overexpressing cells and their correlation with poor patient survival." (PMID 25477524, 2015).
pulmonary fibrosis (3 papers, 2020 to 2025). Chronic progressive interstitial lung disorder characterized by the replacement of the lung tissue by connective tissue, leading to progressive dyspnea, respiratory failure, or right heart failure. "However, neither knockout nor overexpression of Sirt1 influenced the severity of the lung fibrosis phenotype, suggesting that SIRT1 in AT2-lineage cells is dispensable in the pathogenesis of BLM-induced lung fibrosis." (PMID 37653024, 2023).
skin cancer (3 papers, 2014 to 2016). "For example, BLM, WRN, and RECQL4 are mutated in Bloom, Werner, and Rothmund-Thomson genomic instability syndromes, respectively, and XPB and XPD are mutated in Xeroderma Pigmentosum, characterized by high risk of skin cancer." (PMID 25238049, 2014).
bone marrow failure (2 papers, 2020 to 2021).
breast tumors (2 papers, 2020 to 2021). "In addition, high BLM-expressing breast tumors were positive for signature 13, which has been attributed to APOBEC cytidine deaminase activity." (PMID 34966786, 2021).
cervical cancer (2 papers, 2014 to 2015). A primary or metastatic malignant neoplasm involving the cervix. "The overexpression of BRCA1, BRCA2, RAD51, BRIP1 (BACH1), FANCD2, BLM and RFC in non-responding versus responding cervical cancer samples suggests that DNA repair mechanism activation occurs through cell cycle arrest and homologous recombination." (PMID 24708616, 2014). "Our microarray data pointed out an increased level of BLM and RFC1 in the non-responding cervical cancers compared with the responding cancers." (PMID 24708616, 2014).
esophagitis (2 papers, 2016 to 2021). An acute or chronic inflammatory disease affecting the esophageal wall. "Two SNPs replicated their association with radiation-induced oesophagitis (rs7165790 located in the BLM gene: odds ratio (OR) = 0.16, 95% CI = 0.04–0.65, p-value = 0.010; rs4772468 at FGF14: OR = 4.36, 95% CI = 1.15–16.46, p-value = 0.029)." (PMID 33810047, 2021). "Among them, rs7165790 in the BLM gene was significantly associated with decreased risk of esophagitis in both discovery (OR = 0.59, 95% CI: 0.37–0.97, p = 0.037) and validation subgroups (OR = 0.45, 95% CI: 0.22–0.94, p = 0.032)." (PMID 26901225, 2016). "In our study, BLM:rs7165790 was the only SNP validated to be associated with decreased risk of developing esophagitis." (PMID 26901225, 2016). "The most significant SNP for esophagitis was an intronic variant BLM:rs7165790." (PMID 26901225, 2016).
gastric tumors (2 papers, 2022 to 2023). "In the meantime, the loss of BLM function due to MSI can enhance the genetic instability of an already unstable genotype in gastric tumors." (PMID 37626815, 2023).
intestinal tumors (2 papers, 2021 to 2025). "In contrast, BLM transgenic mice expressing human BLM attenuated intestinal tumors when crossed with APC heterozygous mutant mice, thereby indicating that tumor growth can be regulated in a BLM dose-dependent manner." (PMID 33777104, 2021). "BLM heterozygous mutant mice developed T cell lymphoma at a much more rapid rate when challenged with murine leukemia virus and the frequency of intestinal tumor development is higher when crossed with Adenomatous Polyposis Coli (APC) gene heterozygous mutant mice." (PMID 33777104, 2021).
metastatic prostate carcinoma (2 papers, 2022 to 2024). A carcinoma that arises from the prostate gland and has spread to other anatomic sites. "One study examined patients with metastatic prostate cancer who underwent germline genetic testing and found that truncating BLM variants occurred at a higher frequency in patients with metastatic prostate cancer than control populations." (PMID 35782872, 2022).
microcephaly (2 papers, 2022 to 2025). A congenital or acquired developmental disorder in which the circumference of the head is smaller than normal for the person's age and sex. "A male patient with growth retardation and microcephaly was diagnosed with BS at Age 6 after SCE testing and identification of a homozygous BLM Exon 7 variant." (PMID 40641635, 2025).
non-small cell lung carcinoma (2 papers, 2020 to 2024). A group of at least three distinct histological types of lung cancer, including non-small cell squamous cell carcinoma, adenocarcinoma, and large cell carcinoma. "Some other genes, such as BIRC5, BLM, and CCNB2, are also differentially expressed in non-small-cell lung cancer." (PMID 33346087, 2020). "DNA damage repair proteins: BLM, BRCA-1 and PARP-1 expression decreased gradually.LYY-35 can inhibit the proliferation of non-small cell lung cancer A549 cells, block cell cycle, promote apoptosis, increase ROS production, cause DNA damage and interfere with DNA replication." (PMID 38947387, 2024).
Obesity (2 papers, 2023 to 2024). Accumulation of substantial excess body fat. "While FOXP1 was found to be a common interaction partner of PP1MB, SFTPC and TMEM67, an intriguing finding was that the BLM gene was the only common gene among PCa, diabetes mellitus, and obesity, interacting with both FOXP1 and TMPO." (PMID 38235353, 2023). "TNF-α downregulated some of the DNA damage repair genes, which are also altered by obesity: PARP1 (−49.3%, P = 0.008), BLM (−46.9%, P = 0.02), FEN1 (−25.5%, P = 0.04), and PCNA (−38.0%, P = 0.008), but did not affect HDAC1 and Ku70 gene expression." (PMID 39092995, 2024).
rectal cancer (2 papers, 2015 to 2022). A primary or metastatic malignant neoplasm that affects the rectum. "BLM p.P868L has been characterized as an allele that is unlikely to cause BS, but causes partial loss of function manifested by an intermediate sensitivity to hydroxyurea, and has been associated with increased rectal cancer risk." (PMID 26485759, 2015).